OLIG3 (oligodendrocyte transcription factor 3)
Description:
May determine the distinct specification program of class A neurons in the dorsal part of the spinal cord and suppress specification of class B neurons.
Synonyms: bHLHb7; bHLHe20
Tractability: No criterion of Open Targets' tractability assessment is met for any kind of drug.
Gene: Protein-coding gene on chromosome 6 (137,492,199 to 137,494,394, reverse strand). Ensembl gene ENSG00000177468.
Subcellular location: Nucleus
Gene Ontology:
Molecular function: protein binding; sequence-specific double-stranded DNA binding; DNA-binding transcription factor activity, RNA polymerase II-specific; E-box binding; protein dimerization activity
Biological process: axon development; positive regulation of transcription by RNA polymerase II; sensory organ development
Cellular component: chromatin; nucleus
Genetic constraint (gnomAD): Loss-of-function variants: 12 observed, 13.89 expected, observed/expected ratio (o/e) 0.86, 90% interval 0.55 to 1.4. The upper end of that interval is the gene's LOEUF score, 1.4, which puts it in group 5 of 6, group 1 being the genes least tolerant of losing a copy. Missense variants: 405 observed, 363.27 expected, observed/expected ratio (o/e) 1.11, 90% interval 1.03 to 1.21. Synonymous variants: 192 observed, 162.86 expected, observed/expected ratio (o/e) 1.18, 90% interval 1.05 to 1.33.
Homologues: Orthologues: chimpanzee OLIG3 (99% identical), macaque OLIG3 (99% identical), pig OLIG3 (99% identical), rat Olig3 (99% identical), mouse Olig3 (99% identical), rabbit OLIG3 (98% identical), guinea pig OLIG3 (97% identical), tropical clawed frog olig3 (78% identical), zebrafish olig3 (69% identical), Caenorhabditis elegans ngn-1 (16% identical), Drosophila melanogaster tap (14% identical), Drosophila melanogaster ato (13% identical), and 2 more. Paralogues in human: OLIG2 (57% identical), OLIG1 (31% identical), BHLHE22 (30% identical), BHLHE23 (26% identical), NEUROD4 (23% identical), NEUROD1 (22% identical), NEUROD2 (20% identical), NEUROD6 (20% identical), NEUROG2 (16% identical), ATOH1 (16% identical), NEUROG1 (16% identical), BHLHA15 (15% identical), and 3 more.
Diseases named in the same sentence as OLIG3 in open-access papers:
OLIG3 is named in the same sentence as 20 diseases in open-access papers, as found by Europe PMC text mining. Sharing a sentence is not in itself a finding about the gene and the disease. The quoted sentences say what the papers report.
rheumatoid arthritis (3 papers, 2010 to 2018). A chronic, systemic autoimmune disorder characterized by inflammation in the synovial membranes and articular surfaces. "In Family 8 a missense variant (c.628C>G, p.Arg210Gly) was observed in the OLIG3 gene that encodes a transcription factor known to be associated with rheumatoid arthritis and inflammatory polyarthritis." (PMID 30157244, 2018). "This study investigated five confirmed rheumatoid arthritis (RA) susceptibility genes/loci (HLA-DRB1, PTPN22, STAT4, OLIG3/TNFAIP3 and TRAF1/C5) for association with susceptibility and severity in an inception cohort." (PMID 20353580, 2010).
melanoma (2 papers, 2017). A malignant, usually aggressive tumor composed of atypical, neoplastic melanocytes. "Differentially methylated genes included three non-melanoma related genes (MEOX2, OLIG3, PON3), but previously associated with DNA methylation and cancer prognosis in other pathologies." (PMID 28578692, 2017). "Here, we identified, and validated in an independent validation cohort, three genes (MEOX2, OLIG3, and PON3) for which the degree of DNA methylation can predict the prognosis of melanoma patients." (PMID 28578692, 2017).
brain tumor (1 paper, 2019). "The salient features of genes OLIG1, OLIG2 and OLIG3 havingconserved bHLH domain that are associated with brain tumor arediscussed." (PMID 31312081, 2019).
ischemic stroke (1 paper, 2022). A stroke disorder caused by obstruction of blood flow to the brain, due to thrombotic (local blood clot formation) or embolic (due to a blood clot or other material traveling from another site) event. "The specific function and mechanism of Olig3 on oligodendrogenesis in ischemic stroke need further and deeper investigation." (PMID 35547763, 2022).
Obesity (1 paper, 2025). Accumulation of substantial excess body fat. "Transcripts for several candidate genes for obesity were absent in the whole brain or absent in specific regions of the brain (Cyp17a1, Gdf15, Gpr151, Lmx1b, Olig3, Sbk1, Sim1, Skor1, Tnni3k)." (PMID 39920851, 2025).
tumor (3 papers, 2017 to 2025). "In the metastasis-associated neoplastic cell states, we detected robust expression of neural crest (ZIC1, OLIG3), mesenchymal (MSX2, GDF6), and metastasis-related (DKK2) genes in addition to adrenergic genes (e.g., PHOX2B) that were shared with primary tumor cell states." (PMID 41279557, 2025).
musculoskeletal diseases (1 paper, 2018). "Therefore, we carried out a PCR analysis and observed that FIP1L1 and OLIG3 are indeed expressed in these tissues supporting their potential role in musculoskeletal diseases." (PMID 30157244, 2018).
OLIG3 also shares sentences with these, for which no sentence is quoted: ankylosing spondylitis (1 paper); autoimmune disease (1); cancer (1); Cerebral ischemia (1); Crohn disease (1); cutaneous melanoma (1); demyelinating disease (1); Graves disease (1); neurodegenerative disease (1); Stroke (1); systemic lupus erythematosus (1); type 1 diabetes (1); ulcerative colitis (1).